USP22 (ubiquitin specific peptidase 22)
Diseases named in the same sentence as USP22 in open-access papers (continued):
Sharing a sentence is not in itself a finding about the gene and the disease.
tumor (continued). "Besides inflammation-associated colorectal epithelial damage, we detected an increased tumor number as well as size in Apc-mutated Usp22fl/fl mice compared to Usp22 wild type litter mates." (PMID 33920268, 2021). "Importantly, increased USP22 expression is closely associated with neurodegenerative diseases, carcinogenesis, and poor patient survival in a wide range of tumor types." (PMID 33369872, 2021). "Importantly, tumors derived from Villin-CreERT2, Usp22flox mice containing a mutation in the Adenomatous Polyposis Coli (APC) tumor suppressor gene (APC1638N/+) similarly displayed decreased HSP90AB1 levels compared to the Usp22 wild type control tumors." (PMID 31801945, 2019). "Thus, USP22 overexpression identifies patients at high risk and represents a novel therapeutic molecular target for this tumor." (PMID 25909224, 2015). "In addition, given our previous findings that Usp22 loss impacts placental vascularization, it would also be interesting to determine whether overexpression of USP22 in endothelial cells affects tumor progression through enhanced angiogenesis." (PMID 38236941, 2024). "However, USP22-deficiency may introduce a tumor-specific therapeutic vulnerability that makes these tumors attractive targets for HSP90i treatment." (PMID 31801945, 2019). "Given the significance of USP22 in immune cell function and tumour progression, clarifying the molecular regulatory network of USP22 in different types of tumours is necessary." (PMID 41909123, 2026). "As a deubiquitinating enzyme, the function of ubiquitin-specific peptidase 22 (USP22) in tumours has attracted increasing attention." (PMID 41909123, 2026). "In this review, we summarise how USP22 regulates tumour biology and analyse the key role of USP22 in immune regulation to provide new insights into novel therapeutic strategies." (PMID 41909123, 2026). "The knockdown of USP22 expression in the xenograft was confirmed by immunohistochemistry (IHC) staining of USP22 in frozen sections of the tumours." (PMID 40341781, 2025). "Consistent with the results at the cellular level, the protein level of CDK11B was reduced in USP22 knockout tumour tissues compared to the control group." (PMID 40341781, 2025). "The decreased expression of the deubiquitinase USP22 in pancreatic cancer cells promoted the infiltration of natural killer and T cells, thereby enhancing the anti-tumor immune response of the TME." (PMID 39759114, 2025). "Intriguingly, neither genetic nor pharmacological Usp22 inhibition had any effect on EZH2 mRNA expression in MC38, 4T1, and RM1 tumor cells, suggesting that Usp22 regulates EZH2 at the posttranscriptional level." (PMID 41252204, 2025). "USP22 plays a pivotal role in tumor cell tolerance to chemotherapy by promoting the repair of DNA strand breaks." (PMID 40370434, 2025). "In contrast, Usp22 suppression only resulted in a modest reduction in RM1 tumor growth both in RAG1 KO mice, as well as in vitro." (PMID 41252204, 2025). "Targeted CRISPR-mediated deletion of Usp22 resulted in enhanced tumor cell antigen presentation and tumor-specific CD8+ cell immunity." (PMID 41252204, 2025). "In vivo studies further showed USP22 overexpression significantly increased subcutaneous tumor growth and pulmonary metastases in nude mice, effects abrogated by SIRT1 knockout." (PMID 41301681, 2025). "Flow cytometry analysis further confirmed the increase in cell surface expression of H-2Kb/d and β2M in Usp22-null tumor cells." (PMID 41252204, 2025). "Similar to that of Usp22-targeted deletion, treatment of tumor cells with USP22i-S02 led to a substantial reduction in EZH2, but not EED, EZH1, and SUZ12." (PMID 41252204, 2025). "Collectively, these results indicate that USP22 is a de novo interacting partner of EZH2 in tumor cells." (PMID 41252204, 2025).
tumor (continued). "Our results showed a significant suppression of tumour growth in mice receiving USP22 knockout tumours, particularly under Sorafenib treatment, as evident from the reduced tumour volume and weight in the USP22‐depleted groups." (PMID 40341781, 2025). "USP22 also regulates mTOR signaling, and its loss in CRC enhances mTOR activity and tumor burden, further underscoring the diverse context-dependent outcomes of DUB modulation." (PMID 41359051, 2025). "Usp22 inhibition combined with anti-PD1 induced a greater tumor regression and resulted in a higher percentage of CD8+ T cell infiltration compared with mice treated with anti-PD1 alone." (PMID 41252204, 2025). "Clinical analyses further show that high USP22 expression independently correlates with tumor size > 5 cm, microvascular invasion, lymph-node metastasis, and shorter overall survival, serving as a robust prognostic biomarker." (PMID 41301681, 2025). "Tumoral Usp22 inhibition enhances antitumor immune response through upregulating MHC-I–mediated neoantigen presentation to CD8+ T cells." (PMID 41252204, 2025). "Along with EZH2 downregulation, the trimethylation level of histone H3 lysine 27 in Usp22-null tumor cells was reduced." (PMID 41252204, 2025). "Consistent with our results from targeted Usp22 genetic deletion, treatment of mice with preestablished orthotopic 4T1R tumors by USP22i-S02 inhibited tumor growth." (PMID 41252204, 2025). "KDELR1 enhanced the USP22‐mediated invadopodia formation and promoted the ability of tumor cells to penetrate the basement membrane in the in vitro metastasis model." (PMID 39101247, 2024). "Our data clearly indicate that loss of Usp22 strongly impacts Erbb2/Neu RNA and protein expression in MECs isolated from 100-day old MMTV-NIC mice, before the time of the earliest tumor formation, reflecting decreased activity of the MMTV promoter." (PMID 38236941, 2024). "To further reveal the ability of EV‐derived USP22 to promote tumor metastasis, we constructed an in vitro metastasis model." (PMID 39101247, 2024). "LUAD mice xenograft tumor models were performed to investigate the effects of EV‐derived USP22 in vivo." (PMID 39101247, 2024). "First, we used western blotting to verify the expression of USP22 in the tumor tissues of each group." (PMID 39101247, 2024). "We demonstrated that USP22 in tumor cell‐derived EVs promoted tumor metastasis and invadopodia formation and enhanced tumor cell motility in vitro." (PMID 39101247, 2024). "Through ATXN7L3, another component of the nuclear SAGA/STAGA complex, USP22 regulates the tumor immune microenvironment." (PMID 39223632, 2024). "We demonstrate that USP22 controls basal stability of tumor-suppressive PML and identify a destabilizing role of PML K394." (PMID 38467608, 2024). "A total of 4,536 DEGs were identified between tumor (high USP22) and normal (low USP22) groups from the GSE16088 dataset, including 2,386 upregulated and 2,150 downregulated DEGs." (PMID 38784391, 2024). "The deubiquitinase USP22 shows a positive correlation with IFN signaling pathway elements in tumor cells, including JAK1, JAK2, STAT1, and IFNGR." (PMID 39223632, 2024). "In a mouse model injected with a 5-Fu-resistant HCC cell line, targeting USP22 led to a significant tumor size reduction post 5-Fu treatment." (PMID 38702734, 2024). "USP22 is among 11 genes that are strongly correlated with tumour invasion, chemotherapy resistance and prognosis." (PMID 39661501, 2024). "To better understand the role of KDELR1 in tumorigenesis in vivo, we established USP22 control and overexpression tumor models and intratumoral injection of siRNA for KDELR1 (5 nmol/20 g/mice)." (PMID 39101247, 2024). "USP22 is involved in various biological characteristics of tumours, and its molecular function is consistent with its carcinogenic effect." (PMID 39661501, 2024).
tumor (continued). "KEGG and GO enrichment analysis revealed that USP22‐mediated tumor cell‐derived EVs are mainly involved in signaling pathways, such as cell motility and migration." (PMID 39101247, 2024). "Given the significant roles of USP22 and COL17A1 in tumor immune response, future work is required to explore the precise functions of the USP22/COL17A1 axis in the immune response of LUAD." (PMID 39143031, 2024). "USP22 knockdown resulted in smaller tumor volumes and weights compared with those in mice implanted with control shRNA‐infected cells." (PMID 39101247, 2024). "The reduction of USP22 levels was found to suppress tumor growth and enhance the cytotoxicity of T cells." (PMID 38638430, 2024). "The upregulation of ZEB1 also partially reversed the impact of USP22 silencing on the phenotypes of OC cells, indicating that USP22 promotes tumor progression by upregulating ZEB1." (PMID 39530604, 2024). "IHC staining showed that the expression of USP22 and Ki67 was significantly reduced in the tumor tissues of mice in the USP22 knockdown group than in the control group." (PMID 39101247, 2024). "Consistent with previous results, the knockdown of USP22 significantly reduced tumor PD‐L1 expression in a mouse model." (PMID 38520088, 2024). "The in vivo experiments showed that PC9 cells with USP22 overexpression‐derived EVs promoted tumor growth and malignant phenotypic transformation." (PMID 39101247, 2024). "This discovery strengthens our understanding of the role and mechanism of USP22 in the reprogramming of tumour cell metabolism." (PMID 39661501, 2024). "This study suggests a novel tumor-supportive role of USP22 in sustaining cellular respiration to facilitate the drug-tolerant behavior of HER2+-BC and TNBC cells." (PMID 38347585, 2024). "This study demonstrates that 13‐MB inhibits USP22 expression and thus suppresses tumor progression, supporting its potential application as a small‐molecule inhibitor of USP22." (PMID 39101247, 2024). "In GSE16088 dataset, USP22 expression was significantly higher in tumor tissues than normal tissues (p < 0.05)." (PMID 38784391, 2024). "Other studies, however, indicate that USP22 also functions to suppress tumor formation in particular contexts, such as colorectal cancer." (PMID 38236941, 2024). "To further explore the molecular mechanisms by which USP22‐mediated tumor cell‐derived EVs promote tumor metastasis in LUADs, we identified KDELR1 as a downstream effector of USP22 using gene chip and bioinformatics analyses." (PMID 39101247, 2024). "KDELR1 knockdown reversed the role of USP22 in promoting invadopodia formation and tumor metastasis." (PMID 39101247, 2024). "In a liver cancer mouse model, USP22 knockdown significantly enhanced the efficacy of combined PD-L1 targeted immunotherapy and cisplatin by boosting tumor immunogenicity." (PMID 38702734, 2024). "USP22 is overexpressed in CRPC tumor samples, where it deubiquitinates AR/AR-V7, thereby increasing their accumulation." (PMID 38702734, 2024). "The western blotting results suggested that SRSF9 silencing decreased ZEB1, USP22, and N-cadherin expression levels but increased E-cadherin expression levels in tumor tissues." (PMID 39530604, 2024). "In this study, it demonstrates that USP22 increases the secretion of tumor cell‐derived EVs and accelerates their migration and invasion, invadopodia formation, and angiogenesis via EV transfer." (PMID 39101247, 2024). "Even when a higher number of 4T1 cells, 103 and 104, were orthotopically injected, USP22 deletion dramatically inhibited the development of syngeneic tumors, indicating that USP22 is critical for in vivo tumor initiation." (PMID 37398311, 2023). "The knockout of USP22 in pancreatic ductal adenocarcinoma cells results in reduced myeloid cells infiltration and increased tumor infiltration of NK cells and T cells, leading to a synergistic response with combined immunotherapy." (PMID 37415977, 2023).
tumor (continued). "Taken together, our study has demonstrated that USP22 is a novel co-regulator of ZEB1 to enhance ZEB1-induced VEGFA transcription via USP22 deubiquitination activity, thereby promoting tumor growth/invasion/VM formation and angiogenesis in HCC." (PMID 36906615, 2023). "For pancreatic ductal adenocarcinoma (PDAC), targeting USP22 has been shown to enhance the response to immunotherapy and associated with increased proportions of CD8 + T cells and NK cells, which turn “cold” tumor into “hot”." (PMID 37658402, 2023). "Taken together, USP22 accelerates c‐Myc/NrasGV12‐induced tumorigenesis and promotes tumor progression through an FKBP12/mTORC1/autophagy positive feedback loop in HCC cells." (PMID 38045832, 2023). "For example, certain DUBs, including BAP1, UCHL1, CYLD, and USP22, exhibit intrinsic oncogenic or tumor-suppressor activities." (PMID 37626927, 2023). "USP22 is highly expressed in various tumours such as lung, colorectal and gastric cancers, and is involved in DNA transcription, malignant transformation of cells and cell cycle progression." (PMID 36969062, 2023). "In particular, inhibiting USP22 by CRISPR in Treg cells has been demonstrated to lower Foxp3 protein production as well as reduce tumor growth in different tumor types." (PMID 37658402, 2023). "The role of USP22 in the anti-tumor immune TME has been becoming an emerging hotspot, especially its complicated regulating action on different immune cells subsets." (PMID 37658402, 2023). "Knockdown USP22 lowers tumor metastasis dependent of T cells, and enhances NK cells activity, as well as improves anti-PD-1/PD-L1 efficacy." (PMID 37658402, 2023). "In mouse models of hepatocellular carcinoma, knockout of Usp22 increases the infiltration of tumor-infiltrating lymphocytes, augments anti-tumor immunity, and synergizes with anti-PD-L1 treatments and chemotherapy." (PMID 37415977, 2023). "As previously reported, a Usp22-dependent mechanism regulates the expression of PD-L1 on antigen-presenting cells and tumor cells." (PMID 37896966, 2023). "The same results are obtained in liver tumors, when suppressing USP22 increases tumor immunogenicity, encourages T cells infiltration and improves susceptibility to anti-PD-L1 immunotherapy as well as cisplatin-based chemotherapy." (PMID 37658402, 2023). "We then utilized a well-established tumor sphere formation assay 21,22 to evaluate the role of USP22 in breast CSCs self-renewal." (PMID 37398311, 2023). "Researchers have established tumor xenograft models in mice to evaluate the role of USP22 in tumor growth in vivo." (PMID 35784926, 2022). "USP22 has the protein characteristics of CSCs and can promote the formation of various proteins for invasive tumor growth." (PMID 36613989, 2022). "In LIHC and NSCLC, USP22 acts as a deubiquitinating enzyme for PD-L1, inhibiting the ubiquitin-proteasome degradation pathway of PD-L1 and thus leading to tumor immune escape." (PMID 35836933, 2022). "We found that Usp22 is overexpressed in tumor tissues and demonstrate that it is selectively overexpressed in the GBM pseudo-palisade micro layer around the central necrotic area." (PMID 35626719, 2022). "P-p38 MAPK inhibited the expression of USP22, and overexpression of USP22 eliminated the inhibitory roles of P-p38 MAPK on tumor growth, as well as cell proliferation, migration and invasion." (PMID 35356205, 2022). "Here we demonstrate that Usp22 is localized and overexpressed in the pseudo-palisade tissue around the necrotic area of the tumor." (PMID 35626719, 2022). "On the one hand, USP22 can directly regulate the stability of PD-L1 through deubiquitination, leading to tumor immune resistance." (PMID 35935969, 2022).
tumor (continued). "The programmed death ligand 1 (PD-L1)/ubiquitin-specific protease 22 (USP22) axis has been found to control tumor immune escape." (PMID 36591473, 2022). "The expression level of USP22 protein in GC tissue samples was negatively correlated with the degree of tumor differentiation." (PMID 35784926, 2022). "We first examined the expression of USP22 in clinical samples and three RB cell lines, results of which displayed that the mRNA and protein levels of USP22 in tumor tissues were significantly higher than those in the normal retinal cells." (PMID 35356205, 2022). "During glioblastoma development, USP22 exerts a tumor-promoting role through KDM1A deubiquitination." (PMID 35935969, 2022). "Regulation of USP22 can alter the tumor microenvironment, thereby turning cells that are completely resistant to immunotherapy into a sensitive state." (PMID 35935969, 2022). "DEAD-box RNA helicase 3 (DDX3) and ubiquitin-specific peptidase 22 (USP22) genes differ significantly in expression and function according to tumor type." (PMID 35755171, 2022). "In conclusion, USP22 is upregulated in a variety of malignancies, and studies have shown that USP22 induces tumor resistance to 5-FU by acting on CSCs, SIRT1, and C-MYC." (PMID 35935969, 2022). "In many types of tumors, USP22 was identified with a oncoprotein and was in abundance with tumor progression." (PMID 35935969, 2022). "USP22 directly deubiquitinates cyclin D1, protects it from protease-mediated degradation, and promotes tumor proliferation in vivo." (PMID 35935969, 2022). "The expression of USP22 in tumor cells suppresses anti-tumor immunity and confers resistance to immunotherapy." (PMID 35935969, 2022). "Hosts of USP22 shRNA-expressing MHCC-97H cells had smaller tumor volumes and weights than mice implanted with control shRNA-infected cells." (PMID 35449157, 2022). "USP22 exerts tumor-promoting effects in multiple tumor types and suppresses anti-tumor immunity by stabilizing PD-L1 in tumors." (PMID 35924159, 2022). "Similar results have been reported in liver tumors, where ablation of USP22 in liver tumor cells has been shown to increase tumor immunogenicity and promote T-cell infiltration into the resulting liver tumors." (PMID 35935969, 2022). "Histopathologic analysis of GBM tumor specimens allowed the localization and visualization of the overexpression of Usp22 in the pseudo-palisade tissue around the central necrosis area of the tumor." (PMID 35626719, 2022). "For instance, several groups recently reported an important role of USP22 in stabilizing PD-L1 and thereby helping tumor cells to escape immune surveillance." (PMID 34007022, 2021). "USP22 belongs to the deubiquitinating enzyme (DUB) family of proteins involved in tumor relapse and progression." (PMID 34419060, 2021). "In contrast to the general concept of USP22 being a universal oncogene, we and others uncovered a context-dependent tumor suppressor function of USP22." (PMID 33920268, 2021). "Together, these studies suggest an ambiguous and context-dependent role of USP22 where it can have either tumor supportive or tumor-suppressive functions." (PMID 34007022, 2021). "Here, we describe a novel role for USP22 in controlling necroptotic cell death in human tumor cell lines." (PMID 33369872, 2021). "Tumor cell-intrinsic ubiquitin-specific protease 22 (USP22) regulates immune cell infiltration in implanted PDAC tumors." (PMID 34439836, 2021). "Apart from enhancing transcriptional regulation, USP22 controls additional biological processes, like cell growth and differentiation, tumor development, and cell death." (PMID 33369872, 2021).